Y_RNA (Y RNA )
Gene: Miscellaneous RNA gene on chromosome 7 (129,954,693 to 129,954,794, forward strand). Ensembl gene ENSG00000199516.
Homologues: Orthologues: macaque Y_RNA (99% identical), chimpanzee Y_RNA (98% identical). Paralogues in human: Y_RNA (93% identical), Y_RNA (92% identical), RNY3 (91% identical), Y_RNA (91% identical), Y_RNA (90% identical), RNY3P1 (89% identical), Y_RNA (89% identical), Y_RNA (88% identical), Y_RNA (87% identical), RNY3P16 (86% identical), Y_RNA (86% identical), RNY3P14 (85% identical), and 100 more.